INS (insulin)
Diseases named in the same sentence as INS in open-access papers (continued):
Sharing a sentence is not in itself a finding about the gene and the disease.
Insulin resistance (continued). "The study also shows that fasting insulin and glucose concentrations are significantly increased in obese subjects, results are in line with previous findings; the HOMA-Index (indicator for insulin resistance) was significantly (P < 0.001) elevated." (PMID 26942445, 2016). "Due to the nature of the cross-sectional studies and the large cohorts of participants involved, the most common and feasible method used to assess insulin resistance is the homeostasis model assessment (HOMA-IR), derived from fasting glucose and insulin concentrations." (PMID 27258299, 2016). "The association of obesity with T2DM is well established, due to the negative influence of excessive body fat on peripheral insulin action and hepatic function, leading to insulin resistance." (PMID 27303363, 2016). "In muscle, insulin resistance seems to attenuate predominantly IRS1-dependent GLUT4 translocation and glucose uptake, though some reports suggest that IRS2-dependent insulin signaling cascade could also be involved in glucose metabolism in myocytes." (PMID 27247938, 2016). "Considering that insulin suppresses G6pc expression in the liver, we examined whether EPA improves insulin resistance through its direct action on hepatocytes using primary hepatocytes from WT/HFD and InsrP1195L/+/HFD mice." (PMID 27348201, 2016). "Diabetes is usually caused by the interaction of genetic and environmental factors and is characterized by a lack of insulin secretion (relative and absolute) and insulin resistance, always leading to metabolism disorders of fat, protein and carbohydrate." (PMID 27916864, 2016). "Here, we showed that PA reduced insulin‐stimulated tyrosine phosphorylation of insulin receptor substrate 2 and decreased insulin‐stimulated uptake of the fluorescent glucose analog 2‐NBDG, confirming that insulin resistance occurred in PA‐treated H4IIEC3 cells." (PMID 27833848, 2016). "GRK2 has also been recently identified as a negative modulator of insulin signaling and systemic insulin resistance." (PMID 27832814, 2016). "The present findings showed that the beneficial effect of central M617 on insulin sensitivity was same as that of central GAL in adipose tissues, suggesting that the mitigatory effect of central GAL on insulin resistance is mainly mediated by activation of GalR1." (PMID 27127795, 2016). "Mice and humans with obesity and type 2 diabetes manifest ‘selective insulin resistance' in the liver: insulin fails to suppress gluconeogenesis, while it continues to activate lipogenesis, resulting in the combination of hyperglycaemia and steatosis." (PMID 27708333, 2016). "Besides, correlations between TBS and indexes of insulin resistance (HOMA) and insulin sensitivity (QUICKI) were also found after TNF-α blockade." (PMID 27293954, 2016). "Type 2 DM is characterized by hyperglycemia resulting from the combination of insulin resistance and a relative lack of insulin." (PMID 26939025, 2016). "Our results also show that deletion of ATGL specifically in beta cells is, by lowering insulin secretion response, able to protect against HFD-induced hyperinsulinaemia, insulin resistance and obesity, and also able to promote elevated EE by activating BAT, and lipolysis and fat oxidation in WAT." (PMID 27677764, 2016). "Activation of TLR4, another receptor of HMGB-1, activated proinflammatory kinases (such as p38MAPK and JNK) that impaired insulin signal transduction via inhibitory phosphorylation of insulin receptor substrate, suggesting the involvement of HMGB-1 in insulin resistance." (PMID 27847406, 2016). "The study design did not allow for diagnosing and assessing insulin resistance by HOMA-IR in the insulin-dependent patients with type 2 diabetes." (PMID 26772807, 2016).
Insulin resistance (continued). "Here, we tested the effects of selective activation of E2 receptor alpha (ERα) on systemic metabolism, insulin action, and cardiac mitochondrial function in a mouse model of metabolic dysfunction (ovariectomy [OVX], insulin resistance, hyperlipidemia, and advanced age)." (PMID 27582063, 2016). "Known safety concerns were validated, including elevated non-fasting insulin (insulin resistance), and elevated angiotensinogen (salt retention)." (PMID 27530235, 2016). "We also hypothesized that resistance training increases FBM and VBM insulin sensitivity and this is greater in OOM compared to offspring of lean/normal-weight mothers (OLM) due to maternal obesity exposed insulin resistance." (PMID 27669153, 2016). "Moreover, PZI combined with Se decreased the homeostasis model assessment of insulin resistance (HOMA-IR) and increased insulin sensitivity index (ISI) compared with PZI or Se alone." (PMID 27212152, 2016). "Differences in adipogenic capacity between insulin sensitivity and insulin resistance did not reflect reduced cell viability in insulin resistance despite increased markers of oxidative stress." (PMID 27342408, 2016). "This idea of neuronal insulin resistance is in agreement with studies reporting reduced downstream insulin signaling in vivo in the PNS of insulin resistant ob/ob mice in response to either IT and IP injections of insulin." (PMID 28066166, 2016). "The nature of the relationship between insulin hyper-secretion and insulin resistance is not straightforward." (PMID 27559358, 2016). "Consequently, alterations to components of insulin-induced signalling, including impairment of PKB/Akt, are likely to contribute to the pathogenesis of insulin resistance as well as perturbed glucose and lipid homeostasis." (PMID 27613400, 2016). "Insulin resistance, mitochondrial dysfunction, and enhanced production of ROS, which act as secondary messengers by activating serine kinases that phosphorylate IRS proteins, modulate the insulin response." (PMID 27478531, 2016). "We observed that AESN markedly protected against insulin resistance and increased blood glucose, independent of insulin expression." (PMID 26927042, 2016). "Accordingly, we find that chronic metformin affects neither glycemia nor brain insulin signaling in P301S mice, which do not have insulin resistance." (PMID 26858121, 2016). "The AUCs of serum TG or RLP-C levels showed a correlation with the AUCs of plasma insulin (AUC-TG, r = 0.5437, P < 0.0001; AUC-RLP-C, r = 0.6847, P < 0.0001), and they correlated well with the insulin resistance index (AUC-TG, r = 0.7724, P < 0.0001; AUC-RLP-C, r = 0.7645, P < 0.0001)." (PMID 26439243, 2016). "Insulin resistance, weight gain, and adipose tissue weight were diminished, as in the TH model; but, in contrast, circulating insulin levels were not diminished and plasma glucose was not elevated." (PMID 27922820, 2016). "Secondly, these cytokines do not appear to contribute to the reported insulin resistance induced by ORM1 in porcine adipose tissue in vitro as an increase in the abundance of these inflammatory cytokines would be predicted during an insulin resistant state." (PMID 27087941, 2016). "Treatment with fenofibrate significantly reduced triglycerides, non-high density lipoprotein cholesterol (non-HDL-C), insulin levels and insulin resistance index (HOMA-IR) in MetS animals." (PMID 28036029, 2016). "Type 2 diabetes is induced by an imbalance between insulin resistance and insulin secretion and does not occur unless β-cell function cannot compensate for insulin resistance." (PMID 26978400, 2016). "It has been demonstrated that insulin action on Fox0 phosphorylation is IRS-dependent and that inhibition of Fox0 phosphorylation results in the development of hyperglycemia, hyperinsulinemia and insulin resistance." (PMID 27434075, 2016).
Insulin resistance (continued). "In T3D, lack of brain-based insulin production or the presence of brain-based insulin resistance precipitates memory dysfunction with symptomatology that overlaps that of Alzheimer’s disease." (PMID 27563288, 2016). "Moreover, omega-3 rich dietary seems to promote health by decreasing inflammatory state that reduces insulin resistance, increasing GLP-1 secretion that stimulates insulin release, and improving beta-cell function." (PMID 27065349, 2016). "It shows the tendency that TAGs of lower carbon number and double bond content were associated with increased positive correlation to insulin resistance (HOMA-IR) and increased negative association to insulin sensitivity (ISI)." (PMID 27736893, 2016). "Thyroid hormones, insulin, homocysteine, and homeostatic model assessment-insulin resistance were not different between the two groups." (PMID 26761929, 2016). "To test the endogenous role of BI-1 at insulin resistance, we applied the same stress, “palmitate at insulin-treated or non-treated condition” in BI-1 knock-out hepatocytes." (PMID 27576594, 2016). "The pAkt level of SH-SY5YIR cells did not increase after culturing with low concentration insulin (10 nmol/L) showing the presence of insulin resistance (p > 0.05)." (PMID 27884163, 2016). "It has been shown that activation of the IKK-β and JNK pathways increases IRS-1 serine phosphorylation which leads to suppression of insulin signaling and that suppression of the IKK pathway decreases insulin resistance and ameliorates glucose intolerance in diabetic mice." (PMID 27034691, 2016). "Overexpression or administering recombinant adiponectin reduces blood glucose levels and ameliorates insulin resistance in obese mice, which are independent of plasma insulin levels." (PMID 26993044, 2016). "Of note, chronic HCV infection induces insulin resistance not only in the liver but predominantly in skeletal muscle, which is not adequately assessed by parameters of fasting insulin sensitivity like HOMA-IR or QUICKI." (PMID 26735686, 2016). "No insulin plasma levels were measured to correlate with glucose levels to provide further insight into the possible presence of insulin resistance." (PMID 27427983, 2016). "The AUCs of plasma insulin levels or insulin resistance index (IRI): (AUCs of insulin) × (AUCs of glucose) as the insulin resistance marker were greater in diabetic CAD group than non-diabetic CAD group (insulin, P = 0.0373; IRI, P = 0.0228)." (PMID 26439243, 2016). "Furthermore, serum insulin levels in DIO mice were elevated, which was attenuated by isorhamnetin treatment, indicating that isorhamnetin improved insulin resistance." (PMID 26775807, 2016). "The absence of serum insulin and HOMA test to identify impaired glucose tolerance and/or insulin resistance is another deficiency in this study." (PMID 28058131, 2016). "Insulin, glucose-insulin ratio, and homeostatic model assessment-insulin resistance (HOMA-IR) were not different between the groups (p>0.05)." (PMID 26761929, 2016). "At the end of the study there was an improvement of all the metabolic parameters such as glucose, insulin, HOMA-IR (Homeostasis Model Assessment-Insulin Resistance), triglycerides, total and high density lipoprotein cholesterol, body mass index (BMI), waist circumference, and blood pressure." (PMID 27688754, 2016). "Furthermore, the induction of VWAT inflammatory changes coincided with the emergence of systemic and tissue insulin resistance, as illustrated by the increases in HOMA-IR and by the reduced pAKT/AKT responses to exogenous insulin in VWAT." (PMID 27739530, 2016). "Nevertheless, in our series of nondiabetic patients with moderate-to severe- psoriasis, we observed a significant correlation between insulin resistance (negative) and insulin sensitivity (positive) after 6 months of anti-TNF-α therapy." (PMID 27293954, 2016).
Insulin resistance (continued). "Plasma glutamate levels positively correlated with all the somatometric parameters, BW, BMI, WC, VFA and SFA, glucose levels (FPG and 2 h-PG), insulin resistance (HOMA-IR), and insulin secretion (HOMA-β and II) but negatively correlated with insulin sensitivity (OGIS)." (PMID 26788116, 2016). "In murine models, IGFBP-3 inhibits insulin-stimulated glucose uptake, while over-expression of IGFBP-3 in male transgenic mice results in fasting hyperglycaemia, impaired glucose tolerance, and insulin resistance." (PMID 26906713, 2016). "The LC group showed impairment of an insulin-induced glucose lowering, suggesting a LCHD could induce insulin resistance." (PMID 27327650, 2016). "DC seems to occur in experimental measurements on the glucose and insulin responses of people with and without insulin resistance (insets)." (PMID 27875241, 2016). "In conclusion, our study shows that chronic olanzapine treatment induced a significant increase in fasting glucose and insulin levels and insulin resistance without body weight gain." (PMID 27973621, 2016). "PF and PJ treatments significantly decreased serum insulin (p < 0.01, p < 0.001) and HOMA-IR levels (p < 0.05, p < 0.001) in HFD mice, indicating that they could ameliorate insulin resistance." (PMID 27058520, 2016). "Although currently the relationship between insulin or insulin resistance and colorectal cancer is not explicit, no one can ignore the potential effects of insulin at various stages of carcinogenesis." (PMID 26939025, 2016). "Consistent with obese and insulin resistance phenotypes, the HFD-fed mice displayed elevated circulating triglycerides, impaired glucose tolerance, and decreased insulin tolerance and sensitivity." (PMID 27180971, 2016). "Furthermore, we found that leptin plasma concentrations also positively correlated with plasma insulin concentrations and HOMA-IR thus insulin resistance." (PMID 27189377, 2016). "Hyperinsulinemia and peripheral insulin resistance are present in about half of PCOS women mainly in adipose tissue and skeletal muscle while ovarian theca and granulosa cells have been reported to be highly sensitive to insulin." (PMID 27725832, 2016). "Previous studies in morbidly obese patients found an association of increasing TSH, and less significantly decreasing FT4, with insulin and insulin resistance, yet none was controlled for individual confounders." (PMID 27559364, 2016). "Insulin resistance occurs when insulin fails to exhibit its numerous biological effects, and basic symptomatology includes dyslipidemia, obesity, and hypertension." (PMID 27271603, 2016). "But the Mig-6d/d mice had the improved glucose intolerance and insulin resistance without increased amount of phosphoinsulin receptor after insulin infusion in the liver." (PMID 28053990, 2016). "Insulin resistance is defined as the reduction of the metabolic (but not mitogenic) effects of insulin following its binding to the insulin receptor." (PMID 27437032, 2016). "This study showed that jejunal factor/s induce insulin resistance and that these factors activate mTORC2, as revealed by an increased value of Ser473 Akt phosphorylation, even in the absence of insulin stimulation." (PMID 27149630, 2016). "This study illustrated insulin-sensitizing drugs exerted multiple beneficial effects on PCOS women with or without insulin resistance." (PMID 28331909, 2016). "These surrogate indices consists of homeostasis model assessment of insulin resistance (HOMA-IR), quantitative insulin sensitivity check index (QUICKI), Matsuda index, and the new simple index assessing insulin sensitivity using oral glucose tolerance test (SIisOGTT)." (PMID 26752053, 2016). "In addition, exercise interventions resulted in significant differences in the levels of insulin (SMD = 0.94, 95 % CI 0.70 – 1.19; I2 = 93.8 %) and insulin resistance (SMD = -0.35, 95 % CI -0.70 to -0.009; I2 = 0 %)." (PMID 27562357, 2016).
Insulin resistance (continued). "In an open label study of 90 women with insulin resistance and GDM or type 2 diabetes (breakdown of numbers with GDM or type 2 diabetes not specified), a reduction in neonatal hypoglycemia and NICU admissions were found when metformin was added to insulin." (PMID 27435163, 2016). "TNF attenuates the insulin-stimulated tyrosine phosphorylation of insulin receptor (IR) and insulin receptor substrate 1 (IRS1) in adipose tissue and muscle, resulting in the occurrence of insulin resistance." (PMID 28025491, 2016). "An unusual characteristic of the KK-Ay strain is that their insulin resistance is not fully reflected by the insulin tolerance test." (PMID 27922820, 2016). "We examined insulin sensitivity in our CAD patients using the HOMA-IR, a marker of insulin resistance mainly in the liver, and LAP, a continuous variable based on WC and triglyceride concentration, two parameters which reflect tissue lipid accumulation and denote visceral adiposity." (PMID 26788516, 2016). "Indices of insulin sensitivity (the Matsuda index and the reciprocal of the homeostasis model assessment of insulin resistance, 1/HOMA-IR) and an index of beta-cell function, the Insulin Secretion-Sensitivity Index-2 (ISSI-2) were calculated based on the OGTT postpartum." (PMID 27285104, 2016). "The AUCs of plasma insulin levels as the insulin resistance marker were greater in diabetic CAD group than in non-diabetic CAD group (145.3 ± 57.9 vs. 92.6 ± 58.7, P = 0.0373)." (PMID 26439243, 2016). "Insulin resistance and compensatory hyperinsulinemia are key pathogenetic factors in MS, but insulin levels per se are not applied for diagnosis of the MS." (PMID 26910626, 2016). "At this point insulin resistance is present, not only systemically, but also in the heart as determined after acute intravenous insulin injection, but no hypertrophy is yet detected in terms of heart weight/tibial length ratio." (PMID 27832814, 2016). "Analysis of the muscle insulin signaling pathway further confirmed that ERRγ over-expression did not protect against muscle insulin resistance." (PMID 27220353, 2016). "Furthermore, in hepatocytes with insulin resistance, SREBP-1c expression is increased, while the expressions of IRS2 and insulin-induced Akt phosphorylation are significantly decreased." (PMID 27247938, 2016). "Quantitative evaluation of insulin regulation on plasma glucose and free fatty acid (FFA) in response to external glucose challenge is clinically important to assess the development of insulin resistance (World J Diabetes 1:36–47, 2010)." (PMID 26934990, 2016). "The HFD-induced insulin resistance in control mice as shown by the significantly increased fed and fasting blood glucose and serum insulin and HOMA-IR index, and attenuated glucose tolerance and insulin sensitivity was, however, largely prevented in PIKO mice." (PMID 27558934, 2016). "Thus, insulin resistance was identified by HOMA-IR based on single tests of fasting blood glucose and insulin." (PMID 27128847, 2016). "Since insulin resistance is the core of MetS, it is not difficult to understand that subjects with MetS would have higher plasma insulin levels to stimulate all stages of erythropoiesis." (PMID 26758511, 2016). "Higher insulin levels and HOMA-IR values in preterm newborns at birth supports the hypothesis that states which can lead to obesity, hyperinsulinemia, and insulin resistance in later life can have an intrauterine origin." (PMID 27087404, 2016). "Insulin resistance is defined by the lack of insulin's actions in platelets, which downregulates IRS-1/Akt pathway, culminating in elevated intracellular Ca2+ content and proaggregatory mediators." (PMID 28053690, 2016). "To investigate whether local insulin resistance of placentae alters for GDM patients, we examined the key molecules in the insulin pathway." (PMID 27340831, 2016).